DELE1 (DAP3 binding cell death enhancer 1)
Description:
Protein kinase activator that acts as a key activator of the integrated stress response (ISR) following various stresses, such as iron deficiency, mitochondrial stress or mitochondrial DNA breaks. Detects impaired protein import and processing in mitochondria, activating the ISR. May also required for the induction of death receptor-mediated apoptosis through the regulation of caspase activation. [DAP3-binding cell death enhancer 1]: Protein kinase activator that activates the ISR in response to iron deficiency: iron deficiency impairs mitochondrial import, promoting DELE1 localization at the mitochondrial surface, where it binds and activates EIF2AK1/HRI to trigger the ISR. [DAP3-binding cell death enhancer 1 short form]: Protein kinase activator generated by protein cleavage in response to mitochondrial stress, which accumulates in the cytosol and specifically binds to and activates the protein kinase activity of EIF2AK1/HRI. It thereby activates the integrated stress response (ISR): EIF2AK1/HRI activation promotes eIF-2-alpha (EIF2S1) phosphorylation, leading to a decrease in global protein synthesis and the induction of selected genes, including the transcription factor ATF4, the master transcriptional regulator of the ISR. Also acts as an activator of PRKN-independent mitophagy: activates the protein kinase activity of EIF2AK1/HRI in response to mitochondrial damage, promoting eIF-2-alpha (EIF2S1) phosphorylation, leading to mitochondrial localization of EIF2S1 followed by induction of mitophagy.
Synonyms: DELE1(L); DELE; KIAA0141
Tractability: PROTAC: UniProt records ubiquitination sites on it.
Gene: Protein-coding gene on chromosome 5 (141,923,819 to 141,946,919, forward strand). Ensembl gene ENSG00000081791.
Subcellular location: Mitochondrion (DAP3-binding cell death enhancer 1); Mitochondrion outer membrane; Mitochondrion inner membrane; Cytoplasm, cytosol (DAP3-binding cell death enhancer 1 short form)
Subcellular location (Human Protein Atlas): Nucleoplasm; Golgi apparatus
Pathways (Reactome):
Cellular responses to stimuli: Cellular response to mitochondrial stress
Gene Ontology:
Molecular function: protein binding; protein serine/threonine kinase activator activity
Biological process: cellular response to stress; extrinsic apoptotic signaling pathway via death domain receptors; HRI-mediated signaling; positive regulation of mitophagy; response to iron ion starvation
Cellular component: cytosol; mitochondrial inner membrane; mitochondrial outer membrane; mitochondrion
Genetic constraint (gnomAD): Loss-of-function variants: 51 observed, 54.62 expected, observed/expected ratio (o/e) 0.93, 90% interval 0.75 to 1.18. The upper end of that interval is the gene's LOEUF score, 1.18, which puts it in group 5 of 6, group 1 being the genes least tolerant of losing a copy. Missense variants: 597 observed, 619.21 expected, observed/expected ratio (o/e) 0.96, 90% interval 0.9 to 1.03. Synonymous variants: 252 observed, 247.54 expected, observed/expected ratio (o/e) 1.02, 90% interval 0.92 to 1.13.
Homologues: Orthologues: chimpanzee DELE1 (99% identical), macaque DELE1 (94% identical), dog DELE1 (82% identical), pig DELE1 (79% identical), guinea pig DELE1 (76% identical), rabbit DELE1 (75% identical), rat Dele1 (74% identical), mouse Dele1 (73% identical), tropical clawed frog dele1 (34% identical), zebrafish dele1 (14% identical), Caenorhabditis elegans sel-1 (14% identical). Paralogues in human: SEL1L3 (17% identical), SEL1L (16% identical), SEL1L2 (14% identical), LRP2BP (11% identical).
Diseases named in the same sentence as DELE1 in open-access papers:
DELE1 is named in the same sentence as 14 diseases in open-access papers, as found by Europe PMC text mining. Sharing a sentence is not in itself a finding about the gene and the disease. The quoted sentences say what the papers report.
cardiomyopathy (4 papers, 2023 to 2026). A disease of the heart muscle or myocardium proper. "In cardiomyocytes, DELE1 activation is essential for managing mitochondrial stress, and loss of this pathway increases cardiomyopathy." (PMID 40680837, 2025). "To address this question, we crossed the Dele1 KO mouse with four different mouse models of MM/Cardiomyopathy (CM)." (PMID 39379554, 2024). "Impairing GPX4 upregulation induced by OXPHOS deficiency through the inhibition of the integrated stress response, by knocking out either the mitochondrial protease OMA1 or its substrate DELE1, aggravates the cardiomyopathy of Cox10-/- mice by decreasing GPX4 to WT levels, thus inducing ferroptosis." (PMID 37505079, 2023).
Mitochondrial myopathy (2 papers, 2024). "Together our findings identify that the DELE1 mt-ISR mediates a stereotyped response to diverse forms of mitochondrial stress and is particularly critical for maintaining growth and survival in early-onset mitochondrial myopathy." (PMID 38529505, 2024).
colon cancer (1 paper, 2023). "Knockdown of DAP3 and DELE1, respectively, in colon cancer CRC cell lines sensitized the cells to 5-FU, Methotrexate, and Docetaxel, and cells with simultaneous knockdown of DAP3 and DELE1 were markedly sensitive to all the drugs tested, compared with the single knockdown lines and the controls." (PMID 38352299, 2023).
glomerular disease (1 paper, 2026). "As OMA1 is known to cleave multiple substrates, including DELE1, future studies will be necessary to determine the relative contributions of these pathways in podocyte biology and glomerular disease." (PMID 41509918, 2026).
leukemia (1 paper, 2024). A malignant (clonal) hematologic disorder, involving hematopoietic stem cells and characterized by the presence of primitive or atypical myeloid or lymphoid cells in the bone marrow and the blood. "Using the large Leucegene genomic and transcriptomic dataset composed of 48 −5/del(5q) patient specimens and 367 control AML, we identified DELE1 – located in the common deleted region – as the most consistently downregulated gene in these leukemias." (PMID 38102204, 2024).
ovarian carcinoma (1 paper, 2022). A malignant neoplasm originating from the surface ovarian epithelium. "Collectively, our results showed that the mitochondrial PHB2/OMA1/DELE1 pathway cooperated with cisplatin-induced ER stress to amplify the pro-death signals of MIM and MOM, which provided a novel mechanism for increasing the sensitivity of ovarian cancer to cisplatin." (PMID 35163244, 2022).
Parkinson disease (1 paper, 2024). A progressive degenerative disorder of the central nervous system characterized by loss of dopamine producing neurons in the substantia nigra and the presence of Lewy bodies in the substantia nigra and locus coeruleus. "HtrA2, a mitochondrial protease that is associated with Parkinson’s disease, is playing an important role in the cleavage of DELE1 and the activation of HRI-directed integrated stress response during mitochondrial protein import stress." (PMID 38555279, 2024).
type 2 diabetes (1 paper, 2025). "Only seven genes had the same direction of effect for comparison of type 2 diabetes samples and healthy samples in all eight datasets: LOC112268118 and MPO had positive logFC, and IL18BP, DELE1, TSPAN32, ITFG2, and NISCH all had negative logFC." (PMID 41465472, 2025).
tumor (3 papers, 2023 to 2024). "We performed a Western blot analysis on protein extracts from enriched CD45-negative tumor cells to monitor the expression of OMA1, OPA1, and DELE1 isoforms involved in the handling of mitochondrial and ER stress, respectively." (PMID 37024121, 2023). "This suggested that in mutant tumor cells, C403A OMA1 or other proteases might be able to cleave DELE1 under basal conditions." (PMID 37024121, 2023).
hereditary neurodegenerative disorders (1 paper, 2022). "Finally, we sought to study the role of the DELE1 pathway in the context of mitochondrial import and precursor maturation defects observed in hereditary neurodegenerative disorders." (PMID 35388015, 2022).
neurodegenerative disease (1 paper, 2022). A disorder of the central nervous system characterized by gradual and progressive loss of neural tissue and neurologic function. "Genome-wide genetics reveal that DELE1 additionally responds to compromised presequence processing by the matrix proteases PITRM1 and MPP, which are mutated in neurodegenerative diseases." (PMID 35388015, 2022).
DELE1 also shares sentences with these, for which no sentence is quoted: cancer (1 paper); myopathy (1); neuropathies (1).